H4C5 (H4 clustered histone 5)
Description:
Core component of nucleosome. Nucleosomes wrap and compact DNA into chromatin, limiting DNA accessibility to the cellular machineries which require DNA as a template. Histones thereby play a central role in transcription regulation, DNA repair, DNA replication and chromosomal stability. DNA accessibility is regulated via a complex set of post-translational modifications of histones, also called histone code, and nucleosome remodeling.
Synonyms: H4/J; H4FJ; HIST1H4E; TEBIVANED3; TEVANED3
Target class: Other nuclear protein
Gene: Protein-coding gene on chromosome 6 (26,204,610 to 26,205,021, forward strand). Ensembl gene ENSG00000276966.
Subcellular location: Nucleus; Chromosome
Pathways (Reactome):
Gene expression (Transcription): B-WICH complex positively regulates rRNA expression; DNA methylation; ERCC6 (CSB) and EHMT2 (G9a) positively regulate rRNA expression; MLL4 and MLL3 complexes regulate expression of PPARG target genes in adipogenesis and hepatic steatosis; NoRC negatively regulates rRNA expression; PRC2 methylates histones and DNA; RNA Polymerase I Promoter Escape; RNA Polymerase I Promoter Opening; RUNX1 regulates genes involved in megakaryocyte differentiation and platelet function; RUNX1 regulates transcription of genes involved in differentiation of HSCs; Regulation of endogenous retroelements by KRAB-ZFP proteins; Regulation of endogenous retroelements by Piwi-interacting RNAs (piRNAs); Regulation of endogenous retroelements by the Human Silencing Hub (HUSH) complex; SIRT1 negatively regulates rRNA expression; Transcriptional regulation by small RNAs
Chromatin organization: CHD1 and CHD2 subfamily; CHD6, CHD7, CHD8, CHD9 subfamily; ChAHP complex assembly; HATs acetylate histones; HDACs deacetylate histones; HDMs demethylate histones; Interaction of NuRD complexes with transcription factors; NuRD complex assembly; PKMTs methylate histone lysines; RMTs methylate histone arginines
DNA Repair: Cleavage of the damaged purine; Cleavage of the damaged pyrimidine; Nonhomologous End-Joining (NHEJ); Processing of DNA double-strand break ends; Recognition and association of DNA glycosylase with site containing an affected purine; Recognition and association of DNA glycosylase with site containing an affected pyrimidine; Recruitment and ATM-mediated phosphorylation of repair and signaling proteins at DNA double strand breaks
Cell Cycle: Condensation of Prophase Chromosomes; Deposition of new CENPA-containing nucleosomes at the centromere; G2/M DNA damage checkpoint; Inhibition of DNA recombination at telomere; Packaging Of Telomere Ends
Developmental Biology: Activation of anterior HOX genes in hindbrain development during early embryogenesis; Chromatin modifications during the maternal to zygotic transition (MZT); Replacement of protamines by nucleosomes in the male pronucleus
and 20 more pathways
Gene Ontology:
Molecular function: protein binding; RNA binding; structural constituent of chromatin; DNA binding; protein heterodimerization activity
Biological process: negative regulation of megakaryocyte differentiation; nucleosome assembly; chromatin organization; protein localization to CENP-A containing chromatin; telomere organization
Cellular component: CENP-A containing nucleosome; chromosome, telomeric region; extracellular exosome; membrane; nucleoplasm; nucleosome; nucleus; protein-containing complex; extracellular region; chromosome
Genetic constraint (gnomAD): Loss-of-function variants: 15 observed, 6.35 expected, observed/expected ratio (o/e) 2.36. That is too few expected variants to judge how well the gene tolerates losing a copy. Missense variants: 153 observed, 155.39 expected, observed/expected ratio (o/e) 0.98, 90% interval 0.86 to 1.13. Synonymous variants: 154 observed, 61.7 expected, observed/expected ratio (o/e) 2.5.
Gene-disease validity (ClinGen):
ClinGen rates the evidence that H4C5 causes each of these diseases.
Tessadori-Van Haaften neurodevelopmental syndrome 3 (autosomal dominant): Strong.
Homologues: Paralogues in human: H4C1 (100% identical), H4C11 (100% identical), H4C12 (100% identical), H4C13 (100% identical), H4C14 (100% identical), H4C15 (100% identical), H4C16 (100% identical), H4C2 (100% identical), H4C3 (100% identical), H4C4 (100% identical), H4C6 (100% identical), H4C8 (100% identical), and 2 more.
Diseases named in the same sentence as H4C5 in open-access papers:
H4C5 is named in the same sentence as 1 disease in open-access papers, as found by Europe PMC text mining. Sharing a sentence is not in itself a finding about the gene and the disease.
H4C5 shares sentences with these, for which no sentence is quoted: gout (1 paper).